RCC2 (regulator of chromosome condensation 2)
Description:
Multifunctional protein that may affect its functions by regulating the activity of small GTPases, such as RAC1 and RALA. Required for normal progress through the cell cycle, both during interphase and during mitosis. Required for the presence of normal levels of MAD2L1, AURKB and BIRC5 on inner centromeres during mitosis, and for normal attachment of kinetochores to mitotic spindles. Required for normal organization of the microtubule cytoskeleton in interphase cells. Functions as guanine nucleotide exchange factor (GEF) for RALA. Interferes with the activation of RAC1 by guanine nucleotide exchange factors. Prevents accumulation of active, GTP-bound RAC1, and suppresses RAC1-mediated reorganization of the actin cytoskeleton and formation of membrane protrusions. Required for normal cellular responses to contacts with the extracellular matrix of adjacent cells, and for directional cell migration in response to a fibronectin gradient (in vitro).
Synonyms: TD-60
Tractability: Antibody: UniProt places it where antibodies can reach, with high confidence; its Gene Ontology location is reachable by antibodies, with medium confidence. PROTAC: ubiquitination databases record sites on it; its protein half-life has been measured.
Gene: Protein-coding gene on chromosome 1 (17,406,755 to 17,439,772, reverse strand). Ensembl gene ENSG00000179051.
Subcellular location: Nucleus, nucleolus; Nucleus; Cytoplasm, cytoskeleton; Chromosome, centromere; Cytoplasm, cytoskeleton, spindle; Chromosome; Midbody; Cell membrane
Pathways (Reactome):
Cell Cycle: Amplification of signal from unattached kinetochores via a MAD2 inhibitory signal; EML4 and NUDC in mitotic spindle formation; Mitotic Prometaphase; Resolution of Sister Chromatid Cohesion; Separation of Sister Chromatids
Signal Transduction: RHO GTPases Activate Formins
Gene Ontology:
Molecular function: microtubule binding; protein binding; protein domain specific binding; protein kinase binding; RNA binding; small GTPase binding
Biological process: chromosome passenger complex localization to kinetochore; focal adhesion assembly; integrin-mediated signaling pathway; negative regulation of GTPase activity; positive regulation of attachment of spindle microtubules to kinetochore; positive regulation of G2/M transition of mitotic cell cycle; negative regulation of focal adhesion assembly; negative regulation of substrate adhesion-dependent cell spreading; regulation of cell migration; establishment of protein localization; regulation of fibroblast migration; regulation of ruffle assembly
Cellular component: chromosome; chromosome, centromeric core domain; membrane; midbody; mitotic spindle midzone; nucleus; plasma membrane; cytosol; chromosome, centromeric region; cytoskeleton; early endosome membrane; nucleolus; spindle
Genetic constraint (gnomAD): Loss-of-function variants: 18 observed, 52.5 expected, observed/expected ratio (o/e) 0.34, 90% interval 0.24 to 0.51. The synonymous counts are far from expectation, so gnomAD's model fits this gene poorly and the ratio says little. Missense variants: 480 observed, 620.79 expected, observed/expected ratio (o/e) 0.77, 90% interval 0.72 to 0.83. Synonymous variants: 316 observed, 248.98 expected, observed/expected ratio (o/e) 1.27, 90% interval 1.16 to 1.39.
Homologues: Orthologues: chimpanzee RCC2 (100% identical), dog RCC2 (99% identical), mouse Rcc2 (96% identical), rat Rcc2 (96% identical), pig RCC2 (87% identical), rabbit RCC2 (86% identical), guinea pig RCC2 (81% identical), tropical clawed frog rcc2 (78% identical), macaque RCC2 (78% identical), zebrafish rcc2 (78% identical), Drosophila melanogaster CG9135 (43% identical). Paralogues in human: HERC1 (23% identical), RPGR (23% identical), ALS2 (21% identical), RCBTB2 (20% identical), RCBTB1 (19% identical), RCC1L (18% identical), RCC1 (18% identical), SERGEF (18% identical), RCCD1 (11% identical).
Diseases named in the same sentence as RCC2 in open-access papers:
RCC2 is named in the same sentence as 49 diseases in open-access papers, as found by Europe PMC text mining. Sharing a sentence is not in itself a finding about the gene and the disease. The quoted sentences say what the papers report.
breast carcinoma (15 papers, 2018 to 2026). "The regulator of chromosome condensation 2 (RCC2) has been implicated in breast cancer by fostering cell proliferation and migration." (PMID 39118792, 2024). "Although RCC2 has been verified to be a susceptibility gene for breast cancer and colorectal cancer, the function of RCC2 in lung cancer is still unclear." (PMID 38434981, 2024). "In contrast to these results, Overexpression of RCC2 has been associated with shorter overall survival, poor prognosis, and recurrence survival rates in breast carcinoma and lung cancer." (PMID 39118792, 2024). "A recent study reports that RCC2 is significantly highly expressed in breast cancer and is associated with poor overall survival in breast cancer patients." (PMID 33521058, 2020). "Previous studies report that RCC2 is highly expressed in basal-like subtype of breast cancer which is associated with higher propensity for metastasis and worse prognosis compared to other types of breast cancers." (PMID 33521058, 2020). "They found that a high level of RCC2 was associated with a poor overall survival rate among breast cancer patients." (PMID 32565805, 2020). "Samples of breast cancer tissue revealed an increased level of RCC2 and a high level of RCC2 was associated with poor overall survival rate of breast cancer patients." (PMID 31839818, 2019). "Elevated RCC2 expression has also been observed in other tumors such as colorectal cancer, gastric cancer, and lung cancer, suggesting an association between RCC2 and cancer, including breast cancer." (PMID 39118792, 2024). "The association of RCC2 and Rac1 with poor prognostic clinicopathological factors could help in the prediction of tumor progression, and thus targeted therapy could be helpful in the treatment of breast cancer." (PMID 39118792, 2024). "The association of RCC2 and Rac1 with poor prognostic parameters may serve as predictive indicators for aggressive tumors, thus implying that targeted therapy could be beneficial in the treatment of breast cancer." (PMID 39118792, 2024). "Targeting RCC2 lactylation to restrict the rapid proliferation of breast cancer represents a novel proof‐of‐concept strategy." (PMID 40145796, 2025). "PASK, PSENEN, and RCC2 were shown in breast cancer tissues compared to normal breast tissue, which were upregulated and had a favorable link with cancer progression." (PMID 40725242, 2025). "Here, we reported the RCC2 protein as a substrate for lactylation modifications, linking material metabolism and cell division, which in turn promotes the proliferation of breast cancer." (PMID 40145796, 2025). "The regulator of chromosome condensation 2 (RCC2) and RAS-related C3 botulinum toxin substrate 1 (Rac1) have been implicated in the promotion of breast cancer cell proliferation and migration." (PMID 39118792, 2024). "RCC2 in breast cancer triggers the Wnt signaling pathway, leading to the acceleration of EMT and development of cancer cells." (PMID 38993556, 2024). "RCC1 can regulate the development of variety cancer, such as breast cancer, ovarian cancer and so on, so we selected RCC2 as research object for the next stage." (PMID 38434981, 2024). "For example, RCC2 exerts an oncogenic effect on breast cancer by activating the Wnt-signaling pathway, thus driving cell propagation and movement through EMT." (PMID 38008751, 2023). "Previous research revealed that the RCC2 was elevated in breast cancer, ovarian cancer, and lung cancer." (PMID 36441563, 2022). "Expression level of RCC2 is associated with progression of EMT and regulation of activation of Wnt-signaling pathway, which promote development of breast cancer." (PMID 33521058, 2020). "The analysis revealed RCC2 expression at a molecular weight of 56 kDa in all 13 breast cancer samples and all 7 breast fibroadenoma samples." (PMID 32565805, 2020).
breast carcinoma (continued). "MCF-7 cells originating from estrogen receptor-positive (ER+) breast cancer were transfected with anti-RCC2 siRNA or RCC2-expressing plasmids." (PMID 32565805, 2020). "In summary, RCC2 promotes development of breast cancer by inducing EMT and regulating Wnt-signaling pathway." (PMID 33521058, 2020). "We employed a PCR array to investigate molecular pathway of RCC2 in breast cancer by subjecting MCF-7 cells transfected with anti-RCC2 siRNA." (PMID 32565805, 2020). "RCC2 is implicated in Colorectal Cancer (CRC), Lung Adenocarcinoma (LUAD), breast cancer, and ovarian cancer." (PMID 33521058, 2020). "Our study highlights a novel role and a new regulatory mechanism of RCC2 in breast cancer progression." (PMID 31839818, 2019). "Herein, we focused on breast cancer and selected six independent datasets for a meta-analysis, and found that RCC2 mRNA expression was significantly up-regulated in breast cancer tissues compared with normal counterparts (P=0.029)." (PMID 31839818, 2019). "Like before, transwell assays also demonstrated that exogenous RCC2 in breast cancer cells increased migration potential, while ablation of RCC2 markedly reduced their migration capacity." (PMID 31839818, 2019). "Herein, we found RCC2 expression was up-regulated in several kinds of tumors via Oncomine database, including breast cancer." (PMID 31839818, 2019). "Overexpression of RCC2 significantly enhanced cell proliferation and migration abilities of breast cancer cells in vitro and in vivo." (PMID 31839818, 2019). "Kaplan Meier survival analysis of breast cancer patients showed that high expression of RCC2 had significantly reduced overall survival rates." (PMID 31839818, 2019). "Collectively, our study indicates that RCC2 contributes to breast cancer progression and functions as an important regulator of EMT through the activation of Wnt signaling." (PMID 31839818, 2019). "Our studies demonstrated that ectopic expression of RCC2 in breast cancer cells increased cell proliferation in vitro, whereas the silencing of RCC2 led to opposite phenotypes." (PMID 31839818, 2019). "Meanwhile, a comparison of RCC2 expression between 114 pairs of breast cancer tissues with their adjacent normal breast tissues validated the trend above (P < 0.001)." (PMID 31839818, 2019). "Taken together, our results substantiate RCC2 as an oncogene promoting the proliferation and migration of breast cancer cells." (PMID 31839818, 2019). "In the TCGA breast cancer cohort, RCC2 was identified as a gene co‐expressed with MAD2L1." (PMID 40145796, 2025). "Herein, it is demonstrated that the RCC2 protein may serve as a critical link between material metabolism and cell division, promoting the rapid proliferation of breast cancer under high glucose conditions." (PMID 40145796, 2025). "We next examined whether RCC2 K124 lactylation (RCC2K124lac) plays a role in breast cancer cell proliferation." (PMID 40145796, 2025). "Furthermore, our findings proposes an innovative therapeutic approach that involves targeting RCC2 lactylation to inhibit the rapid proliferation of breast cancer cells within a high‐lactate microenvironment." (PMID 40145796, 2025). "They suggested that RCC2 promotes the proliferation and migration of breast cancer cells." (PMID 39118792, 2024). "For instance, IQGAP3, EPHB1, ROR2 and RCC2 were demonstrated to obviously promote cell migration, invasion, and epithelial-to-mesenchymal transition in hepatocellular carcinoma, medulloblastoma and breast carcinoma, respectively." (PMID 34922560, 2021).
breast carcinoma (continued). "Moreover, RCC2 plays an oncogenic role in breast cancer, by activating Wnt-signaling pathway, thus promoting cell proliferation and migration through Epithelial-mesenchymal transition (EMT)." (PMID 33521058, 2020). "We aimed to understand how RCC2 is involved in tumorigenesis in breast cancer." (PMID 32565805, 2020). "In conclusion, RCC2 functions as an oncogene in breast cancer." (PMID 33521058, 2020). "Additionally, exogenous RCC2 expression in breast cancer cells dramatically enhanced the cell migratory capability as indicated by Transwell assays." (PMID 31839818, 2019). "The results indicated that RCC2 was up-regulated in breast cancer tissues (P < 0.001)." (PMID 31839818, 2019). "The expression levels of RCC2 in breast cancer cell lines were then measured." (PMID 31839818, 2019). "Consequently, we generated RCC2-enriched and silenced cells to perform in vitro and in vivo assays, and found that RCC2 overexpression promoted aggressive progression of breast cancer through the activation of the Wnt signaling pathway." (PMID 31839818, 2019). "Interestingly, the highest RCC2 expression was found in the basal-like breast cancer, which is known to have a propensity for metastasis and worse prognosis." (PMID 31839818, 2019). "In this study, RCC2 was found to exert oncogenic activities in breast cancer." (PMID 31839818, 2019). "Taken together, these results indicate that RCC2 is up-regulated in human breast cancer tissues, which may play a significant role in the development of breast cancer and the clinical prognosis of breast cancer patients." (PMID 31839818, 2019). "Next, we investigated the role of RCC2 on malignant phenotypes of breast cancer cells." (PMID 31839818, 2019). "Interestingly, RCC2 could accelerated the EMT progression in breast cancer, prostate cancer and lung adenocarcinoma 33-35." (PMID 38993556, 2024). "Notably, mechanism of RCC2-induced metastasis in LUAD is similar to the mechanism in breast cancer." (PMID 33521058, 2020). "Thus, to elucidate whether the Wnt pathway is involved in RCC2-induced breast cancer progression, expression of β-Catenin in MCF10A cells was examined by immunofluorescence." (PMID 31839818, 2019). "However, the roles of RCC2 in breast cancer are still unclear." (PMID 31839818, 2019). "In breast cancer, KAT2A‐mediated RCC2 lactylation at K124 facilitates RCC2 recruitment of SERBP1, stabilizing MAD2L1 mRNA and promoting progression." (PMID 41454479, 2026). "We found a significant correlation between the expression of RCC2 and MAD2L1 in breast cancer (R = 0.54)." (PMID 40145796, 2025). "The lactylation of RCC2 mediates the activation of the cellular MAD2L1 signaling pathway and contributes to the progression of breast cancer." (PMID 40145796, 2025). "In summary, these results indicate that RCC2, as a lactylation substrate, regulates the MAD2L1 pathway and promotes breast cancer proliferation in a high lactate environment." (PMID 40145796, 2025). "Therefore, RCC2 could play a pivotal role in breast cancer behavior." (PMID 39118792, 2024). "It was reported that RCC2 overexpression promoted Wnt signaling pathway activation and induced EMT promoting an aggressive phenotype in breast cancer." (PMID 36441563, 2022). "Here, we found that RCC2 overexpression promoted mesenchymal phenotypes in mammary epithelial MCF10A cells and western blotting results revealed that RCC2 stimulated EMT in breast cancer cells." (PMID 31839818, 2019). "RCC2-YFP was transiently expressed in three tumor cell lines including HeLa, lung cancer CRL5800 and breast cancer MDA-MB-231." (PMID 29321004, 2018). "Given that RCC2 lactylation activates the MAD2L1 pathway and promotes breast cancer cell proliferation, it may represent a promising therapeutic target." (PMID 40145796, 2025).
breast carcinoma (continued). "Elevated expression levels of RCC2, SERBP1, and MAD2L1 were positively correlated with poor prognosis and shorter survival times in breast cancer patients, suggesting that they may serve as biomarkers for clinical prognosis assessment." (PMID 40145796, 2025). "Additionally, overexpression of RCC2 promotes cell proliferation and migratory capability in MCF7, and MDA-MB-468 human breast cancer cells." (PMID 33521058, 2020). "Moreover, RCC2 expression increases activation of β-catenin transcriptional targets including c-Myc and CyclinD1, further promoting progression of EMT, and resulting in breast cancer metastasis." (PMID 33521058, 2020). "Thus, RCC2 and CASP8 were considered as protective factors in breast cancer." (PMID 33170908, 2020). "However, there is no study on elucidating the correlation between RCC2 and breast cancer progression." (PMID 31839818, 2019).